CCND3 (cyclin D3)
Diseases named in the same sentence as CCND3 in open-access papers (continued):
Sharing a sentence is not in itself a finding about the gene and the disease.
tumor (continued). "The patient with CCND3 amplification in the range of 14–16 additional copies in all 7 metastases did not have a detectable CCND3 amplification in the primary tumor." (PMID 33325154, 2021). "In addition to CCND3 amplifications, amplifications of CCNE1 are common in osteosarcoma as well and the effect of CDK2 inhibition on tumor growth has been demonstrated by dinaciclib (SCH 727965) using patient‐derived xenografts." (PMID 33963544, 2021). "Herein, we reported that miR-138-5p could decrease the expression levels of CDC20, CCND3, Ki67, and MCM in tumor cells." (PMID 32754587, 2020). "Moreover, we detected 15 gene amplifications in six different tumor specimens, including AR, CCND1 (n = 2), FGF19 (n = 2), FGF3 (n =2), KRAS (n = 2), MYC (n = 2), CCND3, CCNE1, CDK6, and RICTOR." (PMID 33203166, 2020). "Following temsirolimus application, cyclin D3 strongly decreased in parental but not in resistant UMUC3 cells while cyclin E was not reduced in parental tumor cells but was distinctly elevated in the resistant cells." (PMID 31167517, 2019). "YAP promoted the expression of PCNA and Cyclin-D3, whereas 14-3-3ζ inhibited their expression Western blot and immunofluorescence assays revealed that 14-3-3ζ overexpression increased the phosphorylation of YAP at the Ser127 site in subcutaneous tumor tissue." (PMID 29069755, 2017). "The mRNA expression of some proliferation and invasion related genes such as CCND3, CCNE1, Ki-67 and MMP3 were all down-regulated in miR-15a/miR-16-1 overexpression group, elucidating the tumor-suppressive functions of miR-15a and miR-16-1 in gastric tumorigenesis." (PMID 25743273, 2015). "Tumor formation in thymi and spleens of v-cyclin transgenic mice correlated with increased levels of p65 Ser536 phosphorylation, increased expression of CDK6 and upregulaton of the NF-κB target cyclin D3." (PMID 23300567, 2012). "The Ki-67 and CCND3 expression level in NSCLC cells in the exercise preconditioning group was much significantly lower than that in the other groups, which indicated that exercise preconditioning could effectively inhibit tumor growth." (PMID 38547196, 2024). "Moreover, variable degrees of intra-patient tumor diversity were observed, except in P46 epithelial CTCs which harbored recurrent altered regions such as chromosome 2 (ALK and MYCN gains), chromosome 6 (CCND3 gain), and chromosome 17 (SEPT9 gain)." (PMID 34272470, 2021). "The expression levels of CD44, CCND3, NCALD, MACF1 and KCTD15 were downregulated in the vast majority of LUAD histological subtypes compared with in normal samples; additionally, they were differentially expressed according to tumor stage and nodal metastasis status." (PMID 33281971, 2021). "miR-138-5p not only down-regulated the expression of cyclin D3 (CCND3), CCD20, Ki67, and MCM in A549/3LL cells, but also regulated the maturation of DCs in A549-bearing nude mice and the 3LL-bearing C57BL/6 mouse model, and DCs’ capability to enhance T cells to kill tumor cells." (PMID 32754587, 2020). "In addition, D cyclins are required for tumor initiation, as mice lacking cyclin D1 are resistant to ErbB2-driven mammary adenocarcinomas, while cyclin D3 null animals are refractory to Notch1-driven T-ALL." (PMID 31226848, 2019). "However, miR-4779 may have potential as a tumor suppressor in cancer patients with low miR-4779 and high PAK2/CCND3 expressions." (PMID 29362401, 2018). "Furthermore, DOT1L regulates the transcription of G1 phase genes CDK6 and CCND3 through H3K79 dimethylation; therefore, blocking DOT1L could result in G1 arrest and thereby impede the cell proliferation in vitro and tumor growth in vivo." (PMID 28114995, 2017). "Furthermore, DOT1L regulates the transcription of G1 phase genes CDK6 and CCND3 through H3K79 dimethylation, thereby knocking down of DOT1L could result in G1 arrest and therefore impede the cell proliferation and tumor progression both in vitro and in vivo." (PMID 28114995, 2017).
tumor (continued). "Moreover, rapamycin has been tested alone or in combination with Janus kinase (JAK), ABL protein inhibitors, focal adhesion kinase (FAK) or also with cyclin D3 (CCND3) and CDK4/6 inhibitors in xenografts mouse model and cancer cell lines, exhibiting synergistic effects on anti-tumor." (PMID 35372343, 2022). "Furthermore, the expression levels of CD44, CCND3, NCALD, MACF1 and KCTD15 were downregulated in the vast majority of LUAD histological subtypes compared with in normal samples, and they were differentially expressed according to tumor stage and nodal metastasis status." (PMID 33281971, 2021). "Examination of D-type cyclin protein overexpression in relation to the TNM stage of the tumours revealed that overexpression of cyclins D1 and/or D2, but not cyclin D3, is linked to colon carcinogenesis and that overexpression of cyclin D2 may be related to a higher TNM stage of the tumour." (PMID 16012517, 2005). "RT-PCR analysis of the transcriptional expression of cell cycle genes showed a significantly increased expression of ccnA1, ccnB2, ccnD3, ccnE1, cdc25b, and E2F1 and a significantly decreased expression of ccnD2 in the Fhit-transfected versus non-transfected tumor cells." (PMID 32545680, 2020).
cancer (104 papers, 2005 to 2026). A tumor composed of atypical neoplastic, often pleomorphic cells that invade other tissues. "Conversely, in GCB cell lines NU-DHL-1 and SU-DHL-6, amplification of cyclin proteins CCND2 and CCND3 oncogenes were found to be associated with uncontrolled growth of cancer cells." (PMID 36831263, 2023). "A t(4:17) translocation at 16.5 embryonic day disrupted Ccnd3; Fgfr2 has tyrosine kinase activity and is frequently mutated in cancer." (PMID 35869059, 2022). "PAI-1 has a growth stimulatory effect in cancer cells, causing cyclin D3/cdk4/6 upregulation and cell cycle progression from G1 to S, initiating the progression of cancer cell developments." (PMID 35682652, 2022). "The results indicated CCND3 overexpression predicted higher risk of cancer progression (HR = 2.29, 95% CI: 1.05‐5.03, P = 0.005)." (PMID 30950241, 2019). "Some of these genes have been implicated in colorectal tumorigenesis, for instance, CCND3 is a known oncogene in multiple cancer types including CRC." (PMID 30952955, 2019). "CCND2 and CCND3 genes and their encoded proteins are also overexpressed in many cancer cases in humans." (PMID 25304455, 2014). "Decreases in phosphorylated-Rb has been associated with the knockdowns of CCND1, specifically the loss of phosphorylation at Ser780 on Rb has been associated with CCND1/CCND3 proteolysis and growth arrest in cancer cells." (PMID 20113529, 2010). "Up-regulation of Ccnd1, Ccnd3, and Jun mRNA (all transcriptional targets of Wnt signaling) are suggestive of increased risk to human cancer." (PMID 16203246, 2005). "In this study, we supposed that CMTM3 may be a gene of Wnt signaling pathways and associated to some pathways in cancer progression along with CCND3, PPP3CA, and PPP3CC." (PMID 34475993, 2021). "Furthermore, we also explored the association between the cyclin D3 expressing levels with the prognostic value among various cancers." (PMID 31198407, 2019). "In particular, we predict isoform switches that affect the encoded protein for the cancer drivers CCND3, MYH11, MITF, RALGD5, ABI1, PRDM1 and PPARG, which may have implications for targeted therapy development." (PMID 25578962, 2015). "Glabridin inhibits cancer cell proliferation and survival by downregulating cyclin D3, CDK2, and CDK4, blocking the G1/S phase transition, and reducing CREB and ATF1 phosphorylation." (PMID 39723390, 2024). "A t(12:14) translocation at the 4th month formed Rad51b-Fbxo34 fusion; Ccnd3 regulates G1/S transition and is frequently dysregulated in many cancer types." (PMID 35869059, 2022). "Among these genes, we focused on CCND2 and CCND3, which were cell cycle regulators and involved in promoting cell proliferation in cancer cells." (PMID 35265169, 2022). "Both cyclin D1 and cyclin D3 are frequently upregulated in various cancers and their aberrant expression is well documented in promoting oncogenesis." (PMID 35406445, 2022). "Cyclin D3 controls cell cycle progression and has been recognized as an adverse predictor in multiple human malignant neoplasms, including CRC." (PMID 35098394, 2022). "The expression of KRT19 in cancer cells increases their cell proliferation rate due to its ability to stabilize cyclin D3." (PMID 34575702, 2021). "Databases involving EMBASE, PubMed and Web of Science were carefully searched, and literatures investigating the prognostic effect of aberrantly expressing cyclin D3 among human cancers were collected for further analysis." (PMID 31198407, 2019). "In ethnicity subgroup, the promoted cancer progression role of CCND3 was observed in Caucasians (HR = 3.75, 95% CI: 1.88‐7.48, P = 0.852)." (PMID 30950241, 2019).
cancer (continued). "We note that cyclin D3, another D-type G1 cyclin important for cancer cell survival and progression, was also up-regulated by CCD in our transcriptomic data." (PMID 31039152, 2019). "And result demonstrated that higher expression level of cyclin D3 was significant correlated to reduction of OS among malignancy patients (HR 1.88; 95% CI 1.31–2.69, p = 0.001)." (PMID 31198407, 2019). "More and more related researches are needed to explore the value of cyclin D3 in different kinds of cancers." (PMID 31198407, 2019). "In accordance, CCND3 is critical for cell growth, proliferation, and cancer development, and is directly targeted by various miRNAs." (PMID 29362401, 2018). "In contrast, CDK6 dependence was almost exclusively seen in cancer cell lines of hematopoietic or lymphoid origin, and these lines also often showed CCND3 dependence." (PMID 30443290, 2018). "Cyclin Ds that contain Cyclin D1, Cyclin D2 and Cyclin D3, are closely related G1 cyclins and are of particular importance to the cancer field." (PMID 29041983, 2017). "Previous studies revealed that abnormal expression of Cyclin D3 was found in many different cancers." (PMID 26412984, 2015). "By focusing on a number of genes, selected because of their reported roles in human cancer (53BP1, CCND3, CLDN7, WNT5B, CAMKK1), we demonstrate the potential impact of this on the translational readout in each cellular context." (PMID 26589636, 2015). "Cyclin D1 was detected in half of the carcinoma tissues and cyclin D3 was observed in only one of the four carcinoma tissues, while cyclin D1 and D3 were slightly detected in normal tissues." (PMID 24765199, 2014). "On the other hand, in case 48, there was similar expression of cyclin D3 protein in normal and cancer tissue." (PMID 16012517, 2005). "Amplifications of CCND1, CCND2, and CCND3 are frequently observed across multiple cancer types." (PMID 38612902, 2024). "Activation of cyclin D3 can either promote cancer cell survival or contribute to cancer cell death." (PMID 35548329, 2022). "Compared to all other indexed types of cancer, CCND3 showed the highest expression levels in B-ALL." (PMID 35013097, 2022). "Therefore, we conducted this meta‐analysis to explore the prognostic role of CCND2 and CCND3 in multiple human malignant neoplasms." (PMID 30950241, 2019). "Additionally, the prognosis role of the expression levels of cyclin D3 in two kinds of cancers was assessed systemically." (PMID 31198407, 2019). "Similarly, p21-activated kinase 2 (PAK2) and Cyclin D3 (CCND3) were identified as direct targets of miR-4779, a miRNA that inhibits cancer cell growth by inducing apoptosis and cell cycle arrest." (PMID 31450613, 2019). "As predicted, knockdown of CCND3 or BIRC5 inhibits the growth of cancer cells." (PMID 29416000, 2018). "Similarly, cyclin D3 is critical for cancer cell growth, proliferation, and development, and is highly expressed in many human cancers." (PMID 29362401, 2018). "Many of the 12q fusion genes produced chimeric proteins or disrupted cancer-associated genes such as RUNX2, CCND3, and LRP1, indicating that some of the fusions may contribute to cancer progression independently of MDM2/CDK4 co-amplification." (PMID 25300797, 2014). "Hence, it is of great importance for us to study whether high-expression cyclin D3 is correlative with poor prognosis and cyclin D3 is a key point of chemotherapy for cancer." (PMID 31198407, 2019).
cancer (continued). "But there existed no significant connection between the elevated expression of cyclin D3 with disease free survival (HR 2.65; 95% CI 0.83–8.46), recurrence-free survival (HR 2.86; 95% CI 0.82–9.96) and progression-free survival (HR 5.24; 95% CI 0.46–60.25) of diffident kinds of malignancy patients." (PMID 31198407, 2019). "Isoforms with increased proportions in stem/TA-like cells (cancer cells) were linked to worse survival, such as COMT-202, TTC39A-216; while increased proportions in stem/TA-like cells (cancer) indicated better prognosis, such as STAG2-203 and CCND3-203." (PMID 40702779, 2025). "Stabilized Notch2 activates downstream signaling components such as C-Myc, Cyclin D3, and HES1, which drive cancer cell survival and chemoresistance." (PMID 40393971, 2025). "We chose CCND1 as a positive control, considering the substantial evidence supporting its role in cancer and the greater depth of CCND1 functional characterization compared with CCND2 and CCND3." (PMID 37081792, 2023). "The CCND1 is always overexpressed in cancer and regulates cell cycle transition from G1 phase to S phase along with CCND2 and CCND3." (PMID 34627268, 2021). "Among cancer‐critical genes (defined in the COSMIC Cancer Gene Census), recurrent high‐level amplifications were found only of ERBB2 in two patients, while EGFR and the cell cycle genes CDK6, CCND2, and CCND3 were amplified in one patient each." (PMID 33325154, 2021). "Copy number amplification events in CCND1, CCND3, CDK6, ERBB2, FGFR1, MET, and PIK3CA also showed higher expression compared to wild types across various cancer types." (PMID 34429404, 2021). "High expression levels of Cyclin D3 CCND3, observed in several types of cancer, promote the G1/S phase transition in the cell cycle." (PMID 33255335, 2020). "PTTG1 has been shown to transcriptionally activate expression of a wide range of target genes, including c-Myc, FGF-2, cyclin D3, p21, and MMP-2, most of which are critically involved in cancer proliferation and metastasis." (PMID 33250768, 2020). "Our results indicated CCND2/3 played an oncogenic role in all of the cancer patients (CCND2: pooled HR = 2.21, 95% CI: 1.67‐2.93; CCND3: pooled HR = 2.29, 95% CI: 1.05‐5.03)." (PMID 30950241, 2019). "In this study, miR-4779 inhibited cancer cell growth by inducing apoptosis and cell cycle arrest, and the putative survival factors PAK2 and CCND3 were identified as direct targets of miR-4779." (PMID 29362401, 2018). "Many proteins involved in stimulation of cell growth, cell survival and cancer development were expressed more strongly in T47D than in MCF7 including for example, cyclin-D3 and prohibitin." (PMID 29113338, 2017). "In this study, we demonstrate that miR-188 exerts anti-cancer potential via downregulating multiple G1/S related genes, including CCND1, CCND3, CCNE1, CCNA2, CDK2 and CDK4." (PMID 25304455, 2014). "Overexpressed genes in the PP adipose tissue of cancer patients that are involved in cell cycle and proliferation include PLCB1, that modulates cyclin D3 and CDK4 in response to the IGF-1 mitogenic stimulus or TPPP3, that regulates G2-M and G1-S transitions." (PMID 23009291, 2012). "Indeed, PTTG1 has been shown to transcriptionally activate expression of a wide range of target genes, including c-Myc, FGF-2, cyclin D3, p21, and MMP-2, most of which are critically involved in cancer proliferation and metastasis." (PMID 33250768, 2020). "Furthermore, CCND3 knockdown in HCT116 cells negatively affected cell proliferation, suggesting that miR-4779 directly targets CCND3 to inhibit cancer cell proliferation." (PMID 29362401, 2018). "Additionally, transfection with miR-4779 led to significant reductions in PAK2 and CCND3 protein expression levels in A549, H460, MCF7, and HT-29 cancer cell lines." (PMID 29362401, 2018). "However, miR-497 can also attenuate the malignancy of cancers by regulating other targets, such as TARBP2, DICER, BCL2, CCND1, CCNE1, CDC25A, CCND3, CDK4." (PMID 24667580, 2014).
cancer (continued). "On the other hand, 12 of the NMR-missing genes in this pathway, such as Dkk4, Sox17 and Ccnd3, have not been reported to be related to any disease including cancer." (PMID 24565050, 2013). "Also at cytoband 6p21.1 is the human cyclin D3 gene CCND3, which is commonly amplified in other cancers, CDC5L (cell division cycle 5-like), and RUNX2 (runt-related transcription factor 2)." (PMID 22685381, 2012). "Since the expression level of each D-type cyclin was different depending on oncogenesis, Ccnd3 may not be abundant in our examined cancer cells." (PMID 39413876, 2024). "However, a role of CCND3 in multiple cancers has been observed, with most CCND3 aberrations being gene-amplification rather than single-nucleotide variants." (PMID 37510349, 2023). "What’s more, owing to the fact that only two researches were enrolled to appraise the connection among the cyclin D3 expressing levels and DFS, RFS and PFS respectively, more and more researches are essential to investigate the connection about cyclin D3 and the development of cancer." (PMID 31198407, 2019). "In addition to targeting CCND3, hsa-miR-16-5p is also known to regulate the expression of various angiogenic (e.g., PTGS2, VEGF, FGFR) and/or carcinogenic factors (e.g. EGFR, BMP7, MAPKs) with key roles in cancer/disease signaling pathways." (PMID 26930275, 2016). "The two experimentally proved targets involved in invasion-inhibiting effect of miR-195 in cancer cells, CCND1 and CCND3, are not influenced by miR-195 in human trophoblastic HTR8/SVneo cells." (PMID 22723898, 2012).